AHR (aryl hydrocarbon receptor)
Diseases named in the same sentence as AHR in open-access papers (continued):
Sharing a sentence is not in itself a finding about the gene and the disease.
acute lymphoblastic leukemia (10 papers, 2011 to 2025). Leukemia with an acute onset, characterized by the presence of lymphoblasts in the bone marrow and the peripheral blood. "Use of demethylating agent caused an increase in the levels of AhR in acute lymphoblastic leukemia (ALL) cells." (PMID 37830596, 2023). "Activation of AhR may be also associated with overcoming of the cell resistance such as methotrexate resistance in acute lymphoblastic leukemia cell." (PMID 32899152, 2020). "The finding that AHR is hypermethylated and repressed in several acute lymphoblastic leukemia (ALL) cell lines and in patients reinforced the idea that AHR repression contributes to malignancy in these models." (PMID 27006469, 2016). "ARNT was examined, since down-regulation of the AHR/ARNT pathway by epigenetic means in acute lymphoblastic leukaemia (ALL) may be extrapolatable to myeloid disease." (PMID 22348345, 2012). "Interestingly, a study on another epigenetic regulator, cytosine DNA methylation, showed that the AHR promoter region is frequently hypermethylated in acute lymphoblastic leukemia." (PMID 22754483, 2012). "Similarly, high levels of AHR promoter methylation have been described in acute lymphoblastic leukemia (ALL) and chronic myeloid leukemia (CML) cell lines, as well as in primary ALL." (PMID 21603610, 2011). "It has been revealed that contrary to normal cells, in acute lymphoblastic leukemia (ALL) AhR promoter gene is methylated and consequently deactivated." (PMID 32899152, 2020). "In acute lymphoblastic leukemia (ALL), hypermethylation of the AHR promoter was found in 33% of patients and impaired binding of SP1 resulting in AHR transcriptional silencing." (PMID 37696456, 2023). "In particular, acute lymphoblastic leukemia (ALL) REH and chronic myeloid leukemia K562 cell lines had high levels of AhR promoter methylation and did not express detectable levels of receptor under basal conditions." (PMID 27243009, 2016).
acute myeloid leukemia (10 papers, 2016 to 2024). Acute myeloid leukemia (AML) is a group of neoplasms arising from precursor cells committed to the myeloid cell-line differentiation. "In the present study, we conducted bioinformatics analysis andin vitro experiments to investigate the role of the AHR in acute myeloid leukemia (AML)." (PMID 38404179, 2024). "We first measured the effect of BA on the AHR expression in different acute myeloid leukemia (AML) cell lines, and the primary CD34 positive hematopoietic stem cells (CD34+) were used as a control." (PMID 29212263, 2017). "Nonetheless, AhR potently impacts hematopoietic progenitor development driving expansion of precursors and AhR signalling may promote differentiation of leukemic stem cells in acute myeloid leukaemia." (PMID 36161514, 2023). "However, MICROGLIAL-AhR potently impacts hematopoietic progenitor development driving expansion of precursors and in acute myeloid leukemia AhR signaling may promote differentiation of leukemic stem cells." (PMID 34456909, 2021). "In acute myeloid leukemia (AML), AhR functions to promote differentiation, and AhR was found to a positive regulator of the response to BETi therapy (inhibitors of bromodomain and extraterminal proteins) in AML." (PMID 37106727, 2023). "In acute myeloid leukemia (AML) cells, the CD34+CD15− population increases following AhR suppression by a block in differentiation rather than by an increase in proliferation." (PMID 27243009, 2016).
cervical carcinoma (10 papers, 2016 to 2025). A carcinoma arising from either the exocervical squamous epithelium or the endocervical glandular epithelium. "In this study, we identified 5,860 genes associated with AHR and involved in the development of cervical cancer(P< 0.05, FDR < 0.05)." (PMID 34784845, 2021). "Another study among U.S. adults found an inverse association between 3-FLU exposure and cervical cancer prevalence, and speculated that this association may be related to the methylation levels of the AhR repressor gene." (PMID 40567989, 2025). "In conclusion, AHR and related genes were closely associated with cervical cancer." (PMID 34784845, 2021). "Recent studies indicate that AHR interacts with Estrogen Receptor alpha, thereby changing its conformation, which causes Estrogen Receptor alpha, transcription factors, and multiple protein complexes to stimulate the progress of cervical cancer." (PMID 34784845, 2021). "Overexpression of AHR was associated with worse prognosis in cervical cancer patients." (PMID 34784845, 2021). "However, the mechanisms underlying the role of AHR in tumor progression and tumor immunology in cervical cancer remain unclear." (PMID 34784845, 2021). "AHR and related genes may be closely associated with cervical cancer." (PMID 34784845, 2021). "Thus, the increased susceptibility induced by the studied polymorphism for cervical cancer might be associated with a greater immune depression associated with AhR." (PMID 26798414, 2016). "The relationship between the expression of AHR and related genes and biological regulation in cervical cancer was analyzed using the LinkedOmics database." (PMID 34784845, 2021). "We investigated the relationship between the expression of AHR and related gene and the prognosis cervical cancer patients using the Kaplan-Meier plotter." (PMID 34784845, 2021). "The Cox multivariate regression results further indicated that high expression of AHR and CYP1A1 was a risk factor for the prognosis of patients with cervical cancer." (PMID 34784845, 2021). "We analyzed the expression of AHR and related genes and its correlation with immune responses, and prognosis in cervical cancer using the Gene Expression Omnibus (GEO), and the Tumor Genome Atlas (TCGA) database." (PMID 34784845, 2021). "We used human cervical cancer (HeLa) cells to investigate how AHR undergoes protein degradation and how its activity is modulated." (PMID 34198826, 2021). "The Cox multivariate regression showed that high expression of AHR (HR = 1.874, 95% CI = 1.069–3.285, P= 0.028) and CYP1A1 (HR = 1.822, 95%CI = 1.077–3.080, P= 0.025) were risk factors for prognosis in patients with cervical cancer." (PMID 34784845, 2021). "Gene set enrichment analysis showed that AHR was involved in a variety of biological regulation processes related to the progression of cervical cancer." (PMID 34784845, 2021). "In this study, we examined the correlation between the expression of AHR and related genes and the immune response in cervical cancer using the TIMER and TISIDB databases." (PMID 34784845, 2021). "With the exception of AIP, AHR and related genes were differentially expressed between cervical cancer and normal tissues was observed in at least one GEO dataset." (PMID 34784845, 2021). "This suggests that the inhibition of AhR/ARNT activity is potentially developed as a therapeutic strategy for cervical cancer." (PMID 32545442, 2020). "Using the GEPIA to analyze the TCGA data, the higher expression level of AhR was positively correlated with shorter disease-free survival of cervical cancer patients." (PMID 32545442, 2020). "This indicated a potential interaction between AHR and related genes in cervical cancer." (PMID 34784845, 2021). "We investigated whether AHR and its related genes were correlated with immune infiltration levels in cervical cancer." (PMID 34784845, 2021). "The mRNA expression of AHR was lower in the normal group than in the cervical cancer group." (PMID 34784845, 2021).
cervical carcinoma (continued). "In the present study, we propose the hypothesis that AHR may play an important role in the occurrence and development of cervical cancer." (PMID 34784845, 2021). "The results indicated that the AHR may be a potential immunotherapy target and biomarker for cervical cancer." (PMID 34784845, 2021). "We used immunohistochemistry to verify the expression of AHR in cervical cancer." (PMID 34784845, 2021). "In addition, Kaplan-Meier plotter showed that high expression of AHR, CYP1A1, HSP90AA1, and HSP90AB1 and low expression of ESR1 were associated with a high hazard ratio for poor overall survival in cervical cancers." (PMID 34784845, 2021). "It is worth investigating the CSC inhibition potential of AhR antagonists in cervical cancer." (PMID 32545442, 2020). "Compared with the normal cervical group, AHR and CYP1A1 are widely expressed in cervical cancer tissues." (PMID 34784845, 2021). "High expression of AHR, CYP1A1, HSP90AA1, and HSP90AB1 and low expression of ESR1 were negatively correlated with the prognoses of cervical cancer patients." (PMID 34784845, 2021). "The expression of AHR and CYP1A1 were analyzed by immunohistochemistry in 30 normal cervical tissue samples and 30 cervical cancer tissue samples." (PMID 34784845, 2021). "In particular, AHR, CYP1A1 and ESR1 were identified as potential prognostic biomarkers and shown to be correlated with immune responses in cervical cancer." (PMID 34784845, 2021). "The analysis of the TCGA data by the GEPIA webtool revealed the strong positive correlation between AhR and Notch1 (R = 0.39, p = 2.5 × 10−12) and between ARNT and Notch1 (R = 0.54, p = 0) in cervical cancer patients." (PMID 32545442, 2020). "For AHR, phosphorylation at PKC sites S12 or S36 adjacent to the bipartite basic amino acid segment of the NLS inhibits ligand-dependent nuclear translocation in monkey kidney fibroblast-like COS7 and cervical carcinoma HeLa cells." (PMID 37696456, 2023). "IHC results indicated that AHR and CYP1A1 were widely expressed in cervical cancer." (PMID 34784845, 2021). "Also in human diffuse large B-cell lymphoma (U-2932 R2 and OCI-LY19), cervical carcinoma (HeLa), hepatoma (HepG2, Huh7), bronchial epithelial cells (16HBE), and in immortalized keratinocytes (HaCAT) TSA significantly induced AHR gene expression and it induced AHR-XRE luciferase activity in HepG2." (PMID 37696456, 2023). "In addition, we showed that levels of AHR and its related genes were correlated with the immune infiltration and expression of immuno-regulators (immunoinhibitors, immunostimulators, MHC molecules) levels in cervical cancer." (PMID 34784845, 2021). "Results in the zebrafish metastasis assay showing that both AHR inhibitors (CH223191, CB7993113) and agonists (DIM) profoundly block TNBC (MDA-MB-231), oral squamous cell carcinoma (HSC3), and/or cervical cancer (HeLa) metastasis imply that a similar situation may exist in other cancer types." (PMID 29735912, 2018). "However, there has not been much research have investigated the role of AHR and in cervical cancer." (PMID 34784845, 2021). "However, the role of AHR in cervical cancer has not been fully elucidated to date." (PMID 34784845, 2021). "Generally, high expression of AHR, CYP1A1, HSP90AA1, and HSP90AB1 and low expression of ESR1 were not conducive to the prognosis of cervical cancer patients." (PMID 34784845, 2021).
Hyperglycemia (10 papers, 2020 to 2026). An increased concentration of glucose in the blood. "The antirheumatic drug leflunomide, also an AhR agonist, demonstrates potential antidiabetic effects by enhancing insulin sensitivity and reducing hyperglycemia, likely mediated through its AhR-dependent anti-inflammatory properties." (PMID 41440753, 2025). "Thus, quantifying the exact contribution of the AhR pathway to overall hyperglycemia in humans is challenging to determine due to its complex and context-dependent role in multiple interacting pathways." (PMID 41440753, 2025). "Concerning TCCD, an acute exposure has been shown to impair glucose-stimulated insulin secretion without hyperglycemia in WT mice but not in AhR (Aryl hydrocarbon Receptor)-deficient mice, suggesting that this effect is mediated though this nuclear receptor." (PMID 36901966, 2023). "However, more studies are needed to explore further the effect of hyperglycemia on the AhR/CYP1A1 pathway." (PMID 36418969, 2022). "However, the quantitative contribution of the AhR pathway to hyperglycemia is not fully defined, as it involves complex, multifactorial processes rather than a single, direct mechanism." (PMID 41440753, 2025). "In contrast, in the absence of Tregs, AhR activation also reduced Nrp1 expression on Th17 cells, which was consistent with our previous study demonstrating 11-Cl-BBQ reduced Nrp1+RORγt+ Th17 cells and protected NOD mice from hyperglycemia." (PMID 38035105, 2023).
intestinal infections (10 papers, 2014 to 2025). "Deficiency of the AhR repressor leads to fewer IELs, which can cause intestinal infection and inflammation." (PMID 38711967, 2024). "Innate lymphoid cells drive immune responses against intestinal infections, and their generation is impaired in AhR-deficient mice." (PMID 24966027, 2014). "Dysregulated AHR activity adversely affect intestinal infection and inflammation through intestinal intraepithelial lymphocytes loss." (PMID 37179416, 2023). "Some studies have shown that AHR is crucial for maintaining intestinal health and inhibiting intestinal infections." (PMID 37179416, 2023). "I3Ald and I3LA act as AhR ligands and activate AhR, which in turn activates IL-22 expression, and IL-22 plays an important role in reducing the severity of many intestinal infections." (PMID 35606749, 2022). "ILC3s act on intestinal epithelial cells and modulate resistance to intestinal infections via the expression of IL-22, which is dependent on aryl hydrocarbon receptor (AhR)." (PMID 34831296, 2021). "In this study we tested whether prolonged activation of AHR per se is an inducement of detrimental activity that would perturb the normally beneficial AHR function in an intestinal infection." (PMID 40502009, 2025). "Given that the intestinal microenvironment is substantially influenced by AHR activity in multiple cell types, we chose the intestinal infection model with C. rodentium to probe the consequences of either TCDD application or endogenous constitutive AHR activity." (PMID 40502009, 2025). "The AHR gene protects the GI against inflammation and prevents intestinal infections." (PMID 39795948, 2024).
intestinal inflammation (10 papers, 2020 to 2026). "In the LPS-stimulated mouse intestinal inflammation model, IAld treatment can also activate AhR signaling and inhibit downstream inflammatory pathway activation." (PMID 39334766, 2024). "This study assesses the influence of tryptophan metabolism, and particularly the microbiota-induced AhR expression, on intestinal homeostasis disturbance following gastroenteritis resolution, and evaluates the efficacy of IL-22 cytokine vectorization on PI-IBS symptoms." (PMID 35090380, 2022). "Notably, current evidence indicates a reduction in aryl hydrocarbon receptor (AhR) expression within the intestinal tissue of IBD patients; at the same time, the mucosal barrier is restored in mouse models of intestinal inflammation through AhR signaling via IL-22." (PMID 41530817, 2026). "Previous studies have shown that AhR activation by potent AhR agonists such as 6-Formylindolo [3,2-b] carbazole (FICZ) and β-naphloflavone (βNF) improves intestinal permeability and tight junction integrity in in vitro and mouse models of intestinal inflammation." (PMID 38068838, 2023).
mastitis (10 papers, 2021 to 2025). Inflammation of breast tissue during lactation or postpartum due to an obstructed duct or infection. "To investigate the protective effects of AhR activation in mastitis, we detected the AhR levels in the mammary glands of mice with mastitis caused by E. coli, which is one of the predominant pathogens involved in human and animal mastitis." (PMID 34297785, 2021). "AhR activation is associated with improving barrier integrity and limiting inflammatory signaling, which are involved in mastitis pathogenesis." (PMID 34297785, 2021). "In this study, we revealed that AhR was involved in the pathogenesis of E. coli-induced mastitis and that treating with Ficz ameliorated E. coli-induced mastitis in association with inhibiting inflammation and repairing the barrier function by activating AhR." (PMID 34297785, 2021). "Importantly, injury to tryptophan-based metabolites and AhR activation are also associated with mastitis in individuals." (PMID 34297785, 2021). "Lactobacillus reuteri (L. reuteri) treatment attenuated E. coli-induced mastitis by promoting tryptophan metabolism and activating AhR, leading to reduced NF-κB activation and improved barrier function in mice." (PMID 41139776, 2025). "Administration of 5-HIAA alleviates mastitis by inhibiting NF-κB activation through aryl hydrocarbon receptor (AhR) signaling." (PMID 41139776, 2025). "In conclusion, the results suggested that IPA inhibited S. aureus-induced mastitis through inhibition inflammation and restoring blood-milk barrier by activating AhR." (PMID 41170435, 2025). "Supplementation of L. reuteri with the ability to produce Aryl hydrocarbon receptor (AhR) ligands ameliorated E. coli-induced mastitis in an AhR-dependent manner." (PMID 38500127, 2024). "AhR activation lightens E. coli-induced mastitis by strengthening tight junction protein expression and limiting NF-κB pathway activation." (PMID 36678175, 2023). "In conclusion, FOR had protective effects against LPS-induced mastitis via suppressing inflammation and enhancing blood-milk barrier integrity via AhR-induced Src inactivation." (PMID 35185907, 2022). "We further investigated the effects of AhR activation on barrier integrity and the NF-κB signaling pathway, which is the primary inflammatory signaling pathway involved in E. coli-induced mastitis development." (PMID 34297785, 2021). "To verify the effects of AhR activation on E. coli-induced mastitis, we inhibited AhR activation by pretreating mice with CH223191, an AhR antagonist." (PMID 34297785, 2021). "Using an E. coli-induced mastitis model in mice, we pharmacologically activated the AhR pathway and showed that AhR activation alleviates E. coli-induced mastitis." (PMID 34297785, 2021). "To confirm the role of intestinal microbiota in AhR activation and mastitis development, we treated mice with dietary tryptophan with or without gut dysbiosis." (PMID 34297785, 2021). "Several studies have indicated a potential role for AhR in mastitis pathogenesis, and alterations in AhR ligand levels have been reported in mastitis." (PMID 34297785, 2021). "Mammary glands from mice with E. coli-induced mastitis have higher AhR expression, leading to the involvement of the AhR pathway in mastitis immunopathology." (PMID 34297785, 2021). "We found that mice treated with E. coli displayed higher AhR expression, implying the regulatory role of the AhR pathway in E. coli-induced mastitis pathogenesis." (PMID 34297785, 2021). "To investigate the effects of the intestinal microbiota on AhR activation of the mammary gland and mastitis development, we treated mice with ABX to disrupt the intestinal microbiota." (PMID 34297785, 2021). "Collectively, these results identify the beneficial role of AhR producer intervention on E. coli-induced mouse mastitis." (PMID 34297785, 2021). "Impaired AhR activation by disturbing the intestinal microbiota initiated mastitis, and processed Escherichia coli (E. coli)-induced mastitis in mice." (PMID 34297785, 2021).